HLA-DQA1 (major histocompatibility complex, class II, DQ alpha 1)
Diseases named in the same sentence as HLA-DQA1 in open-access papers (continued):
Sharing a sentence is not in itself a finding about the gene and the disease.
AIDS (2 papers, 2021 to 2025). A syndrome resulting from the acquired deficiency of cellular immunity caused by the human immunodeficiency virus (HIV). "On the other hand, they showed that HLA-DQA1*01:02, HLA-DPB1*01:01, HLA-B*58:01, HLA-B27, HLA-B51, and HLA-B57 are protective alleles for HIV disease progression to AIDS, while the haplotype DRB1*03:01-DQA1*05:01-DQB1*02:01 is associated with disease progression." (PMID 41614782, 2025). "Among infertile women, HLA-DQA1*05/B1*02 was more prevalent in women with AIDs than in those without (p = 0.009, OR 4.6, 95% C.I. 1.4–14) as well as in women with AITD than in those with other AIDs (p = 0.04, OR 7.3, 95% C.I. 1.12–84)." (PMID 34579148, 2021).
Alzheimer disease (2 papers, 2023). A progressive, neurodegenerative disease characterized by loss of function and death of nerve cells in several areas of the brain leading to loss of cognitive function such as memory and language. "Moreover, from the selected genes, HLA-DQA1 has been reported previously as a risk factor in late-onset Alzheimer’s disease using GWAS and differential expression analysis." (PMID 37833700, 2023).
autoimmune hepatitis (2 papers, 2023 to 2025). Hepatitis caused by autoantibodies. "In addition, PBC patients carrying HLA-DRB1*15:01:01 and HLA-DQA1*03:03:01 would have a higher predisposition toward developing concomitant autoimmune hepatitis (AIH)." (PMID 37325616, 2023).
cervical dysplasia (2 papers, 2021). "The UK Biobank and FinnGen study also performed a GWAS restricted to cervical dysplasia and reported rs9272245 (HLA-DQA1) as a signal for dysplasia alone." (PMID 34680286, 2021).
Diabetic Nephropathy (2 papers, 2013 to 2024). "Variants of the HLA-DQA1 gene have been associated with various autoimmune conditions, including T1DM, and have been proposed as markers of susceptibility for T2DM and diabetic nephropathy." (PMID 39258111, 2024).
endometriosis (2 papers, 2020 to 2021). The growth of functional endometrial tissue in anatomic sites outside the uterine body. "A literature search identified similar reports from China, which showed an association between endometriosis and the HLA-B*46, HLA-DRB1*15, and HLA-DQA1*0401 alleles." (PMID 32184413, 2020).
gestational diabetes mellitus (2 papers, 2024 to 2025). "The genetic variations in the HLA-DQA1 and HLA-DQB1 genes may collectively contribute to the susceptibility to gestational diabetes mellitus." (PMID 40771282, 2025).
hepatitis B (2 papers, 2022 to 2024). "The HLA-DQA1*01:03:01 allele was also significantly less expressed in our hepatitis B group versus healthy subjects." (PMID 38392185, 2024). "Although research on the introns of HLA lags far behind, a recent study suggested that HLA-DQA1 alleles were associated with protection from hepatitis B virus infection." (PMID 35905417, 2022). "For example, Chinese patients exhibit heightened hepatitis risk with HLA B*48 and DRB1*48 genotypes, whereas acute hepatitis B patients in the same population have lower occurrences of HLA-DRB1*11:01/11:04 and HLA-DQA1*03:01 compared to those with chronic hepatitis." (PMID 38392185, 2024).
infertile (2 papers, 2021 to 2023). "Additionally, the prevalence of the HLA-DQA1*5 allele was found to be elevated in our sample since the majority (>50%) of the infertile women were carriers." (PMID 36968684, 2023). "The strong positive association of HLA-DQA1*5 allele carriage with the overall compatibility of the HLA-DQA1 alleles highlighted in our study suggests that the HLA-DQA1*5 allele could be used as a surrogate marker for evaluating overall immunological compatibility in infertile couples." (PMID 36968684, 2023).
male infertility (2 papers, 2016 to 2023). The inability of the male to effect fertilization of an ovum after a specified period of unprotected intercourse. "Most SNP-populated genes related to male infertility include HLA-DQB1 (20 SNPs), HLA-DRB1 (15 SNPs), MTHFR (10 SNPs), BRCA2 (9 SNPs), ACE (8 SNPs), CFTR (6 SNPs), CDH1 (6 SNPs), SRD5A2 (6 SNPs), HLA-DQA1 (5 SNPs) and MMP9 (5 SNPs)." (PMID 29263816, 2016).
narcolepsy (2 papers, 2020 to 2024). A sleep disorder characterized by a tendency for excessive sleepiness during the day which occurs even after adequate sleep in the nighttime. "We observed that the most common susceptibility genes in patients with narcolepsy in this study were HLA-DQB1*0602/*0301/HLA-DQA1*0102/*0505." (PMID 38725645, 2024). "Differences in clinical and somatosensory characteristics among patients with narcolepsy with different HLA-DQA1*0102 genotypes." (PMID 38725645, 2024). "In summary, this study demonstrated a correlation between different genotypes of HLA-DQA1*0102/DQB1*0602 and cataplexy in Chinese patients with narcolepsy." (PMID 38725645, 2024).
osteosarcoma (2 papers, 2020 to 2024). A usually aggressive malignant bone-forming mesenchymal neoplasm, predominantly affecting adolescents and young adults. "HLA-DQA1 is also an HLA class II variant that has been reported to be associated with the osteosarcoma risks." (PMID 32665038, 2020). "VAMP8, A2M, HLA-DRA, SPARCL1, HLA-DQA1, APOC1 and AQP1 were identified continuously upregulating during the oncogenesis and metastasis of osteosarcoma." (PMID 32665038, 2020). "Although there are no definitive studies supporting a clear link between HLA-DQA1 and osteosarcoma, several studies seem to reveal a positive correlation with certain malignancies." (PMID 38684858, 2024).
ovarian carcinoma (2 papers, 2018 to 2020). A malignant neoplasm originating from the surface ovarian epithelium. "Despite the similarity of type I and II ovarian cancer, HLA-DQA1 showed a completely different expression pattern, in which the expression level in type II ovarian cancer was obviously higher than that in type I ovarian cancer." (PMID 32793247, 2018). "Besides, MHC molecules, including HLA-B (cor = 0.365, p = 5.69e-11), HLA-DMA (cor = 0.413, p = 7.02e-14), HLA-DPA1 (cor = 0.475, p = 2.03e-18), HLA-DQA1 (cor = 0.467, p = 8.07e-18), and HLA-E (cor = 0.447, p = 2.6e-16), were significantly correlated with the expression of SUCNR1 in ovarian cancer." (PMID 33062639, 2020).
periodontitis (2 papers, 2020 to 2025). An acute or chronic inflammatory process that affects the tissues that surround and support the teeth. "Frequencies of HLA-A9 and -B15, HLA-DQA1*03:01, HLA-DQB1*03:02 and HLADQB1*03:05 alleles, as well as that of the HLA-DRB1*04:01 allele, were significantly higher in patients with aggressive periodontitis compared with control subjects among Caucasians and Iranian patients." (PMID 32515416, 2020). "However, unlike other loci, such as HLA-DQA1* and HLA-DQB1*, which did not display significant associations with the severity or extent of periodontitis in the sample, this work identified an interesting pattern connected to two alleles of the HLA-DRB1 locus: HLA-DRB1*03 and HLA-DRB1*15." (PMID 40283738, 2025).
preeclampsia (2 papers, 2017 to 2021). Preeclampsia is a hypertensive disorder of pregnancy that is characterized by new-onset hypertension with proteinuria presenting after 20 weeks of gestation, and depending on mild or severe forms may initially present with severe headache, visual disturbances, and hyperreflexia. "In this study, the frequencies of HLA gene polymorphisms, HLA-DQA1*0102, and HLA-DQB1*0602 were investigated among healthy subjects and patients with preeclampsia." (PMID 29662965, 2017). "Additionally, we found 2 genes, Major Histocompatibility Complex, Class II, DQ Alpha 1 (HLA-DQA1) and Inositol 1,4,5-Trisphosphate Receptor Type 1 (ITPR1) that were reported in previous studies of preeclampsia." (PMID 35719905, 2021).
pulmonary TB (2 papers, 2016 to 2025). "Polymorphisms in HLA-DQA1 have been associated with protection and susceptibility to pulmonary TB in many studies." (PMID 40762982, 2025). "In a study to analyze HLA-DRB1, DQA1 and DQB1 allelic polymorphism in Iranian patients with pulmonary TB, HLA-DRB1*07 and HLA-DQA1*0101 alleles apparently conferred susceptibility to TB while HLA-DQA*0301 and HLA-DQA*0501 conferred protection against this infection." (PMID 26803588, 2016).
sarcopenia (2 papers, 2020 to 2022). Progressive decline in muscle mass due to aging which results in decreased functional capacity of muscles. "Having two HLA-DQA1*03:01 alleles increased odds of sarcopenia by 19.3% (OR 1.19, CI 1.09–1.29, p = 2.84*10–5), compared to no alleles." (PMID 30772894, 2020). "A previous study on genetic markers for sarcopenia identified the loci near FTO, ESR1, NOS3, KLF5, and HLA-DQA1 to be associated with physical phenotypes, such as low handgrip strength and decreased LBM24–26." (PMID 35241739, 2022).
astrocytoma (1 paper, 2023). "However, in the TCGA astrocytoma cohort, there was a negative association of A2AR with PD-L1, TIM-3, and HLA-DQA1, and only a positive correlation with LAG-3." (PMID 37047660, 2023).
basal cell carcinoma (1 paper, 2020). A carcinoma involving the basal cells. "Basal cell carcinoma has 1 gene (HLA-DQA1 with variance 2%) out of its top 20 genes included among the 641 potentially problematic genes, while 28% is the highest fraction of predictor variance accounted for by a single gene." (PMID 32694572, 2020).
bladder cancer (1 paper, 2022). "The expression of the 3 genes in urothelial cancer ranges from moderate for NKIRAS2 (NCBI), variable for AKTIP (HPA), and variable for HLA-DQA1 as determined by an immune transcriptome analysis in bladder cancer." (PMID 35039759, 2022).
Burkitt lymphoma (1 paper, 2024). A rare form of malignant mature B-cell non-Hodgkin lymphoma. "A study of 4,645 children in four countries in East Africa, 800 with Burkitt lymphoma (BL), identifies an association between HLA-DQA1*04:01 and variant rs2040406(G) and elevated risk of BL in Africa." (PMID 38182727, 2024).
Cataplexy (1 paper, 2024). A sudden and transient episode of bilateral loss of muscle tone, often triggered by emotions. "Different genotypes of HLA-DQA1*0102/DQB1*0602 are associated with symptoms of cataplexy in Chinese narcoleptic patients." (PMID 38725645, 2024). "Second, the different genotypes of HLA-DQA1*0102/DQB1*0602 are closely related to the presence or absence of cataplexy but not to hallucinations, sleep paralysis, or RBD." (PMID 38725645, 2024).
chordoma (1 paper, 2025). Chordomas are rare malignant tumors arising from embryonic remnants of the notochord in axial skeleton. "The expression analysis identified significant downregulation of SPOCK3, NRK, MYH8, DLK1 and SLN, alongside upregulation of HLA-DQA1, GDA, CXCL11, CXCL9 and ADAMDEC1 in chordomas." (PMID 40386066, 2025).
colitis (1 paper, 2021). Inflammation of the colon. "As indicated by regression analysis, the link between HLA-DQA1*05 and the extent of colitis proved stronger than with gender." (PMID 34946883, 2021). "In summary, HLA-DQA1*05 correlates with a greater extent of colonic inflammation at diagnosis in children with UC." (PMID 34946883, 2021).
Cryptosporidium infection (1 paper, 2021). "In this current study HLA-B*38:02 and HLA-DQA1*01:01 were associated with increased risk of Cryptosporidium infection." (PMID 33910121, 2021).
dermatomyositis (1 paper, 2025). Dermatomyositis (DM) is a type of idiopathic inflammatory myopathy characterized by evocative skin lesions and symmetrical proximal muscle weakness. "Genetic factors play a significant role in the pathogenesis of dermatomyositis, alleles HLA-DRB1*03:01 and HLA-DQA1*05:01 are strongly associated with disease susceptibility." (PMID 41293157, 2025).
duodenitis (1 paper, 2024). Acute or chronic inflammation of the duodenum. "Additionally, we found two overlapping genes (HLA-DQA1 and HLA-DQB1) across T2D, IBD, and gastritis-duodenitis." (PMID 38802514, 2024). "Others included 41 GWS genes for GERD (Pgene-GERD < 2.62 × 10−6), 11 for PUD (Pgene-PUD < 2.62 × 10−6), three (RNF5, HLA-DQA1, and HLA-DQB1) for gastritis-duodenitis (Pgene-gastritis-duodenitis < 2.62 × 10−6), and three (HLA-C, PITPNM2, and MPHOSPH9) for IBS (Pgene-IBS < 2.62 × 10−6)." (PMID 38802514, 2024).
dysplasia (1 paper, 2021). A usually neoplastic transformation of the cell, associated with altered architectural tissue patterns. "A recent trans-ethnic GWAS meta-analysis including the Estonian population proposed two signals at the HLA locus, rs1053726 (HLA-B) and rs36214159 (HLA-DQA1), from a specific analysis that only included dysplasia cases." (PMID 34680286, 2021).
giant cell arteritis (1 paper, 2024). "These signals belonged to five different loci, two of which are established risk loci for giant cell arteritis, 6p21.32 (HLA-DQA1, rs41269974; p=1·60 × 10–87; OR 2·03 [95% CI 1·90–2·17]) and 6q26 (PLG, rs4252114; p=1·38 × 10–13; OR 1·25 [1·18–1·32])." (PMID 38734017, 2024).
glioma (1 paper, 2024). A benign or malignant brain and spinal cord tumor that arises from glial cells (astrocytes, oligodendrocytes, ependymal cells). "The genes analyzed included HLA‐DQA1, HLA‐DQB1, HLA‐DMB, LY86, MS4A7, FOLR2, and MS4A4A in glioma patients." (PMID 38997808, 2024).
gout (1 paper, 2023). A condition characterized by painful swelling of the joints, which is caused by deposition of urate crystals. "Therefore, the high expression of HLA-DQA1 in NCMs with antigen processing and presentation may be an underlying immune mechanism during gout flares." (PMID 38063198, 2023). "We found that the expression of HLA-DQA1 increased in NCMs during gout flares but gradually decreased in CMs." (PMID 38063198, 2023). "In addition to a slight increase in the number of interactions involving MHC-II signaling during gout flares, we observed a distinct activation of the ligand HLA-DQA1 and its cognate receptor CD4." (PMID 38063198, 2023). "Here, based on single-cell RNA-Seq and an independent validation cohort, we identified the potential mechanism of gout flare, which likely involves the upregulation of HLA-DQA1+ nonclassical monocytes and is related to antigen processing and presentation." (PMID 38063198, 2023). "Based on our findings, we propose that the upregulation of HLA-DQA1 in NCMs with antigen presentation during gout flares is not specific to urate crystals; rather, it is implicated in damage-associated molecular patterns produced by the inflammation associated with gout flare." (PMID 38063198, 2023).
graft versus host disease (1 paper, 2016). An immune system disorder that occurs after allogeneic hematopoietic stem cell transplant and is a reaction of donor immune cells against host tissues. "The pathway enrichment for trans-eQTL egenes was largely driven by HLA genes (e.g. HLA-DRB4, HLA-C, HLA-B, HLA-DPA1, and HLA-DQA1 appear in the gene sets for graft-versus-host disease, allograft rejection, and cell adhesion molecules)." (PMID 27140173, 2016).
Granuloma (1 paper, 2025). A compact, organized collection of mature mononuclear phagocytes, which may be but is not necessarily accompanied by accessory features such as necrosis. "However, our study presents new evidence for the expression of HLA-DPB1 and HLA-DQA1 in macrophages within CS granulomas." (PMID 40521183, 2025).
Hepatitis (1 paper, 2023). Inflammation of the liver. "In addition to the association with the DRB1 allele, 23 out of 27 samples from patients with hepatitis were positive for HLA-DQA1*03:03 compared with 11 out of 64 samples from controls (allele frequency of 0.54 compared with 0.09, respectively, OR of 12.3 (5.1–30.7), P = 1.9 × 10−11)." (PMID 36996873, 2023).
hepatitis C infection (1 paper, 2011). "The progression-related sub-network deregulated in hepatitis C infection stage was constructed with four nodes (HLA-DQA1, HLA-DQB1, HLA-DPA1 and CD74) and interactions among them." (PMID 21526182, 2011).
Hypertension (1 paper, 2024). The presence of chronic increased pressure in the systemic arterial system. "We also identified Translocase Of Outer Mitochondrial Membrane 40 (TOMM40) variants associated with CAD; Solute carrier family 22 member 2 (SLC22A2) variants associated with CAD and CVD; and HLA-DQA1 variants associated with hypertension." (PMID 39258111, 2024). "The HLA-DQA1-rs6938008 variant was also associated with hypertension in the overall cohort (Supplementary Document 2)." (PMID 39258111, 2024). "Our study identified a consistent association for HLA-DQA1 with hypertension and serum lipids, with up to nine variants associated with LDL, TG and DBP in all cohorts." (PMID 39258111, 2024). "HLA-DQA1 was associated with hypertension and all the serum lipids." (PMID 39258111, 2024). "Our study suggests a potential role for HLA-DQA1 in biological context for the development of hypertension in patients with altered serum lipid levels." (PMID 39258111, 2024). "Our results place NOS3 gene as the common nexus between CAD, CVD and hypertension, with serum lipids connected to CVD through SLC22A2, in combination with TOMM40 for CAD and to hypertension through HLA-DQA1." (PMID 39258111, 2024).
idiopathic dilated cardiomyopathy (1 paper, 2024). Decreased function of the heart associated with cardiac enlargement and congestive heart failure, of unknown cause. "The HLA-DQA1*0501 allele confers susceptibility to idiopathic dilated cardiomyopathy, while the DQA1 0201 allele provides protection." (PMID 39258111, 2024).
juvenile chronic arthritis (1 paper, 2012). "rs9272346 is a promoter SNP related to the HLA-DQA1 gene which was previously shown to be associated with juvenile chronic arthritis." (PMID 22970175, 2012).
Kawasaki disease (1 paper, 2024). A rare inflammatory disease characterized by an acute febrile, systemic, self-limiting, medium-vessel vasculitis primarily affecting children. "Consistent with our findings, a study reveals that CM highly express S100A8, S100A9, and S100A12, IM express HLA-DQA1 and HLA-DPA1 and NCM mainly express CD16, demonstrating a distinct transcriptome across monocyte subsets in Kawasaki disease." (PMID 39318997, 2024).
liver diseases (1 paper, 2018). "HLA-DQ proteins, a group of heterodimeric molecules consisted of alpha- and beta-chains encoded by HLA-DQA1 and HLA-DQB1 genes, were implicated in immune-mediated diseases, including liver diseases and cancer." (PMID 29416599, 2018).
lung adenocarcinoma (1 paper, 2025). A carcinoma that arises from the lung and is characterized by the presence of malignant glandular epithelial cells. "In lung adenocarcinoma, high expression of CCL20, IL23A, MMP1 and MMP3 was significantly associated with poor patient prognosis, whereas high expression of FOS, HLA-DPA1, HLA-DPB1, HLA-DQA1, HLA-DQB1 and HLA-DRA was significantly associated with improved patient prognosis." (PMID 40016789, 2025).
lupus nephritis (1 paper, 2006). Glomerulonephritis in the context of systemic lupus erythematosus. "Similarly, the absence of an association of HLA-DRB1, HLA-DQB1, and HLA-DQA1 alleles with renal involvement in our cohort may represent a power issue for HLA-DRB1*15 (HLA-DR2) and other alleles previously reported to be associated with lupus nephritis." (PMID 17076550, 2006).
Lyme disease (1 paper, 2016). Lyme disease (named after the towns in the USA where the disease was first identified) is a bacterial infection caused by Borrelia burgdorferi. "While no DEGs were identified on the basis of single versus multiple lesions, four DEGs were found to be upregulated in seronegative Lyme disease patients relative to those who were seropositive, namely, HLA-DQA1, HLA-DQB1, HLA-DRB5, and NSA2." (PMID 26873097, 2016). "Here we found that upregulation of certain HLA genes (HLA-DQA1, HLA-DQB1, HLA-DRB5) is associated with seronegativity in Lyme disease and may thus constitute potential diagnostic biomarkers for seronegative patients." (PMID 26873097, 2016).
metabolic diseases (1 paper, 2022). "Associations with nutritional and metabolic diseases were also less important, and were mainly linked to the genes RMST, HK1, HLA-DQA1 and LAMP2." (PMID 36430729, 2022).